MUC1 (mucin 1, cell surface associated)
Diseases named in the same sentence as MUC1 in open-access papers (continued):
Sharing a sentence is not in itself a finding about the gene and the disease.
tumor (continued). "Angiogenesis is essential during the development of tumor and multiple proangiogenic factors such as vascular endothelial growth factor-A (VEGF-A) and PDGF-B can be induced by MUC1 under hypoxia, which promote the synthesis of new blood vessels within the tumor masses." (PMID 26367866, 2015). "The anti-MUC1 antibody (Mouse Anti-Human CD227 antibody) was labeled with a near-infrared dye [Cy5.5-N-hydroxysuccinimide (NHS)] and a green dye (fluorescein-NHS) and evaluated in OVCAR3 tumor-bearing mice." (PMID 25663888, 2015). "Efforts to elicit CTLs against tumor MUC1 with peptide based vaccine have not been successful in clinical application." (PMID 26417929, 2015). "MUC1/CIN85 complex also regulates migration and invasion of tumor cells in vitro." (PMID 25675408, 2015). "Mucin 1 (MUC1), in particular, has been identified as a highly O-glycosylated transmembrane protein that is dysregulated at the expression and posttranslational level in multiple tumour types." (PMID 26052355, 2015). "Various vaccination strategies and immunotherapies targeting the MUC1 N-terminal VNTR have been developed to treat MUC1-positive cancers; many of these have proven capability of inhibiting tumor growth, reducing metastasis, and prolonging survival in MUC1 transgenic mice." (PMID 26417929, 2015). "It is possible that anti-MUC1 antibody in ER negative tumor does not afford the same protective effect in patients with ER positive BC." (PMID 26693201, 2015). "Thus, compared with neoplasms of other organs, MUC4 expression is of little significance in SBCs, similarly to MUC1." (PMID 24722639, 2014). "A therapeutic potential of the anti-MUC1 SP antibodies was suggested by their ability to support of complement-mediated lysis of MUC1-positive tumor cells but not MUC1 negative tumor cells and normal naive primary epithelial cells." (PMID 24416403, 2014). "Cell-surface presence of MUC1 SP was detected, using the raised antibodies, on tumor cell-lines and primary tumors, but not on naïve primary cells." (PMID 24416403, 2014). "A moderate to strong nuclear expression of ADAM10 was noted in tumor cells presenting a cytoplasmic expression of MUC1 while this was faint or absent when MUC1 expression was restricted to the membrane." (PMID 24504508, 2014). "Recent studies have examined the cell-free mRNA expression of several genes, including TS, β-catenin, hTERT, CK19, MUC1, CXCR4, Bmi-1, Her-2 and DKK1, these studies have focused on the use of cell-free mRNA for early diagnosis, tumor staging and disease monitoring." (PMID 25496700, 2014). "An immunohistochemical analysis of the tumor samples indicated positivity for WT1 and MUC1." (PMID 25526950, 2014). "In a first study, the authors showed that a CD4+ T-cell response against MUC1 occurred in Wt mice following challenge with MUC1-expressing B16 tumor cells, whereas this response was absent in TG mice." (PMID 23509794, 2013). "Next, to assess the phenotypic characterization of DC/tumor, the mean fluorescence intensity (MFI) of HLA-DR and CD86 expression by DC/tumor were determined by FACS analysis, where the fused cells were identified as MUC1+HLA-DR+ or MUC1+CD86+." (PMID 23555011, 2013). "Next, we demonstrated that the production of active TGF-β1, IL-10 and VEGR from tumor cells was significantly inhibited by a simple treatment of pharmaceutical grade ethanol without the down-regulation of MHC class I and the MUC1 tumor-associated antigen." (PMID 23717436, 2013). "CTLs induced by any types of DC/tumor lysed PANC-1 cells (HLA-A2+MUC1+) but not autologous monocytes (HLA-A2+MUC1-), MIA PaCa-2 (HLA-A2-MUC1+), and K562 (HLA-A2-MUC1+) cells (data not shown)." (PMID 23555011, 2013). "In vivo investigations using vaccination against MUC1 with glycosylated or nonglycosylated peptide suggest that tolerance is not established against epitopes of MUC1 carrying a tumor-specific pattern of glycosylation, such as the Tn antigen." (PMID 23509794, 2013).
tumor (continued). "Problems here partly relate to the conformational differences between non-glycosylated vaccine sequences and tumor-expressed, aberrantly glycosylated MUC1." (PMID 26343966, 2013). "Indeed, we observed that some tumor cell lines recognized by the CD8+ T-cell clone were weakly stained with the SM-3 antibody and another mAb specific for hypoglycosylated MUC1, VU-3-C6." (PMID 23509794, 2013). "Mucin 1 (MUC1) belongs to the “overexpressed TAA” category, even if this overexpression is not the only hallmark of MUC1 in tumor cells, since it is often accompanied by modification of MUC1 glycosylation status." (PMID 23509794, 2013). "The tumor exhibited nests of malignant cells with diffuse CK7 and MUC1 positivity." (PMID 24367734, 2013). "Oppositely, NANOG-knockdown cells generated tiny tumor nodules with lower levels of SOX2 and MUC1." (PMID 23662114, 2013). "The MUC1 TG mouse tumor model seems to back up the idea of tolerance against MUC1 in humans, but the modifications of MUC1 glycosylation observed in human cancer cells were not taken into account in these studies." (PMID 23509794, 2013). "Consistent with previous findings, expression of MUC1 in MMT mice did not alter mammary tumorigenesis or metastasis since comparable tumor sizes and numbers of lung colonies were observed between MT and MMT mice." (PMID 22277639, 2012). "Using a full-length MUC1 antibody, we found expression in 80% of the tumours, with neither correlation with prognostic indicators nor survival." (PMID 22454081, 2012). "Here, we showed that numbers of Treg cells in MUC1-expressing tumors were greater in MUC1.Tg mice than in control C57BL/6 (B6) mice, and that the growth of tumor cells expressing MUC1, but not that of control cells, in MUC1." (PMID 23028615, 2012). "The model that included the three biomarkers (MUC1, MSLN, and MUC2) was superior to the model including four conventional pathologic features (lymph node status, histologic grade, tumor size, and resection margin status), although the difference just missed statistical significance (p = 0.07)." (PMID 22792233, 2012). "The results suggested that intercalation of doxorubicin into MUC1 aptamer did not significantly interfere with the binding of the aptamer to MUC1-positive tumor cells." (PMID 22384115, 2012). "EGF treatment significantly enhanced pulmonary metastasis of FG cells expressing a control shRNA as expected, but shRNA-mediated knockdown of MUC1 expression selectively blocked EGF-induced pulmonary metastasis without preventing primary tumor growth." (PMID 22586492, 2012). "Here, we show that EGF stimulation promotes MUC1 cleavage, which is both necessary and sufficient to initiate tumor cell metastasis but has no impact on primary tumor growth." (PMID 22586492, 2012). "Current experimental techniques are biased towards the identification of shared tumor antigens such as HER2/neu, MUC1, and mammaglobin-A, and no experimental techniques are capable of rapidly or systematically identifying unique tumor antigens." (PMID 24213133, 2011). "The scFv binding to MUC1 positive tumour cells T47D, MCF-7, SKOV3 and to MUC1 negative HEK293T cells was analysed by FACS." (PMID 21264246, 2011). "High amounts of MUC1 shed into the environment of tumors could block ICAM-1 binding sites on immune effector cells and contribute to the anergic state of tumor-infiltrating lymphocytes." (PMID 24212946, 2011). "Furthermore, injection of DCs, ex vivo targeted with conjugates of glycan modified tumor antigen MUC1 (oxidized mannan-MUC1), in mice lead to in the generation of high frequencies of MUC1-specific CTL and protection from tumor challenge." (PMID 24212951, 2011). "Studies to link Muc-1, NDPK, inflammatory cells, the endothelial cell and its P2Y receptors may further our understanding of tumor cell mediated metastasis." (PMID 22091350, 2011). "At the present state of knowledge, these findings do not imply that MUC1 can be used as a tumor marker." (PMID 20929551, 2010).
tumor (continued). "Essentially all the tumor cells demonstrated strong cytoplasmic MUC1 staining, but were negative for MUC2, MUC4, MUC5AC and MUC6." (PMID 20550696, 2010). "The tumor cells showed ductal-like cytoplasmic MUC1 staining, but were negative for MUC2 and other mucin gene markers." (PMID 20550696, 2010). "Although MUC1-specific antibodies and/or CTLs were detected in some patients, they were not adequate to generate effective anti-tumor immunity." (PMID 19534821, 2009). "In our experiments, however, anti-MUC1 antibody responses were much higher in the pcDNA3.1-VNTR vaccinated mice, and this may play an important role in mediating tumor protection." (PMID 19534821, 2009). "Despite all the immunised mice developing a strong humoral response we did not observe consistent tumour protection when the mice were vaccinated with MUC1-pep-STn or MUC1-prot-STn." (PMID 19436292, 2009). "In pancreatobiliary differentiated tumours, MUC1 and/or MUC4 expression was an independent prognostic factor (hazard ratio 2.02, 95% confidence interval 1.02, 3.98) when adjusting for nodal involvement, vessel involvement and tumour size." (PMID 19236510, 2009). "MUC1 is a transmembrane molecule whose major extracellular domain is composed of various tandem repeat units (VNTR) consisting of 20 amino acids (GVTSAPDTRPAPGSTAPPAH) and is the most specific epitope for tumor immunotherapy." (PMID 19534821, 2009). "Vaccination of wild-type mice with MUC1 RNA-transfected DCs (DCs/MUC1 RNA) induced anti-MUC1 immune responses against MUC1-positive MC38/MUC1, but not MUC1-negative tumor cells." (PMID 20182533, 2009). "Out of seven cancer-associated gene-markers used to detect tumor cells in PBL and BM, CK19, muc1 and ErbB2 were not informative due to the high expression in normal control samples." (PMID 18289390, 2008). "Further, our evidence indicated that MUC1* functions as a growth factor receptor on tumor cells, while the full-length protein appeared to have no growth promoting activity." (PMID 18833326, 2008). "The role of MUC1 in the healthy state has not been studied as extensively as its role in cancer, where there is significant evidence that it promotes tumor cell growth and survival." (PMID 18833326, 2008). "Moreover, tumor cells also secrete molecules such as AFP and MUC1, all of which affect the maturation and function of DCs." (PMID 18793383, 2008). "Positive expression of MUC1 and MUC3 was seen in 32% and 74% of tumours respectively." (PMID 17349047, 2007). "The vaccination regimen consisted of vaccinia virus expressing tumor antigens carcinoembryonic antigen (CEA) and mucin-1 (MUC-1) with three costimulatory molecules B7.1, ICAM-1 and LFA-3 (TRICOM) (PANVAC-V) and fowlpox virus expressing the same antigens and costimulatory molecules (PANVAC-F)." (PMID 18039393, 2007). "This aversion has been reported to result from non-functional cytoplasmic glycosylates (MUC1) with subsequent lack of tumour-cell binding to E-selectin at the endothelial surface." (PMID 17242702, 2007). "We propose that tumours lacking expression of MUC1 and MUC3 will be more likely to metastasise, due to previously observed loss of cell-cell adhesion, and this will therefore lead to more aggressive cancers with poorer prognosis." (PMID 17349047, 2007). "Kaplan-Meier analysis demonstrated a significant reduction in disease specific survival with MUC1 positive tumours (p = 0.038), this was not seen with MUC3 (p = 0.552)." (PMID 17349047, 2007). "When dividing the tumours according to previous studies 276 (68%) tumours were MUC1 negative and 127 (32%) positive." (PMID 17349047, 2007).
tumor (continued). "MUC1 tumor expression was studied by immunohistochemistry employing two anti-MUC1 antibodies: CT33, anti cytoplasmic tail MUC1 polyclonal antibody (Ab) and C595 anti-peptidic core MUC1 monoclonal antibody." (PMID 17064405, 2006). "Our results also showed that serum MUC1 levels were elevated in 15% of HNSCC samples; interestingly, we found a statistically significant correlation between serum and tumor MUC1 detection indicating that this mucin may possibly be released by the tumor." (PMID 17064405, 2006). "We initially generated an scFv molecule from the variable domains of the humanised mAb huHMFG1 that specifically bound to MUC1+ tumour cells but did not exhibit sufficient stability." (PMID 15150594, 2004). "Utilising the C595 scFv, we generated an anti-MUC1-scFv-Fc-IL2 fusion protein that after binding to MUC1-positive tumour cells induces proliferation of peripheral blood T cells and mediates activation of resting NK cells to lysis of MUC1-positive tumour cells." (PMID 12966437, 2003). "For instance, MUC1, which is expressed in over 90% of BC and 95% of TNBC cases, has been targeted using MUC28z‐CAR T cells that recognize aberrantly glycosylated MUC1, leading to antigen‐specific cytotoxicity and significant tumor reduction in xenograft models." (PMID 41049266, 2025). "Preliminary data suggested that MUC1 CAR T-cells could mediate cytotoxicity without overt off-tumor toxicity, though responses were predominantly disease stabilization." (PMID 40940995, 2025). "Using PDX models that retained the antigenic profiles of the primary tumors, it was shown that PSCA-targeted CAR-T cells could effectively inhibit NSCLC tumor growth in PDX mice and synergistically eradicate PSCA + MUC1 + tumors in combination with MUC1-targeted CAR-T cells." (PMID 40428391, 2025). "In this context, the main strategies to boost NK-cell function against CRC could rely on the use of mAbs or BiKEs targeting CRC tumor antigens (e.g., EGFR, CEA, HER2, MUC-1 and LGR5) that can directly induce tumor cell death but also simultaneously trigger NK cell cytotoxicity via ADCC." (PMID 40607422, 2025). "Furthermore, the staining intensity of Tn‐MUC1 was not related to tumor size, proliferation ability (Ki‐67), or HER2 staining intensity." (PMID 40844495, 2025). "Modified MUC1 protein-functionalized AuNPs were found to be potent macrophage activators, promoting the release of IL-6, IL-10, IL-12, and TNF-α from peritoneal macrophages and driving predominant M1 polarization, highlighting their potential as a potent tumor vaccine." (PMID 40801739, 2025). "Although mucinous differentiation did not independently predict survival, extracellular mucus and MUC1 expression could promote tumour progression through immunosuppression." (PMID 39966658, 2025). "Importantly, the in vivo CTL assay revealed a significant antigen-specific cytotoxic T lymphocyte response in mice immunized with NLE-formulated MUC1 mRNA, confirming that the vaccine is capable of eliciting functional CD8+ T cell responses against tumor antigens." (PMID 40943370, 2025). "The increased tumor growth observed in female mice vaccinated with MUC1 3Adj C3-liposomes could not be explained by a lack of adaptive immune response given the robust T-cell and antibody response in this vaccination group." (PMID 40284463, 2025). "We evaluated the expression of IGF1R and IR isoforms in a panel of four different cell lines: H295R and JIL-2266, derived from ACC primary tumours of female patients, MUC-1 and TVBF-7, derived from ACC distant and perirenal lymph-node metastasis of male patients, respectively." (PMID 40038716, 2025). "However, additional combination of MUC1 LCP-mRNA with an anti-CTLA4 antibody was needed to enhance CD8+ T cell recruitment, inhibit the tumor-promoting STAT3 pathway, and further enhance anti-tumor responses in the murine triple negative breast cancer cells, in vivo." (PMID 41012179, 2025).
tumor (continued). "Notably, in all cases, Tn‐MUC1 and VVL were positive only in the same tumor regions." (PMID 40844495, 2025). "Thus, the present study aimed to evaluate the expression of the circulating tumor markers CK20 and MUC1 in peripheral blood samples from GC patients, who underwent gastrectomy, and to verify the association of their expression levels with clinicopathological characteristics and survival." (PMID 38324850, 2024). "Interestingly, recent data suggests that the inclusion of a CTLA4 inhibitor in conjunction with a MUC1 mRNA nanovaccine enhances the therapeutic impact of the anti-CTLA-4 monoclonal antibody and adjusts the immune resistance within the tumor immune microenvironment (TME)." (PMID 38397971, 2024). "The current review offers an exhaustive exploration of the roles of MUC1 and MUC16 in the context of cancer biomarkers, elucidating their critical contributions to the mechanisms of cellular signal transduction, regulation of immune responses, and the modulation of the tumor microenvironment." (PMID 38361923, 2024). "Therefore, it is predicted that EGFR-MUC1 dual-targeting therapies could improve the response of tumor cells, and analysis of EGFR and MUC1 co-expression patterns in clinical samples are essential to provide a solid rationale for drug development." (PMID 39664199, 2024). "Recent evidence suggested that several other molecules, including HGF, membrane-bound mucin glycoprotein (Muc-1), indoleamine 2,3-dioxygenase (IDO), as well as soluble primary histocompatibility complex class I -related chain A (sMICA), can also be found in the tumor microenvironment." (PMID 38464531, 2024). "Tumoural and CAF scores were first calculated for the union of tumour and CAF spots based on the expression signatures of the genes MUC1 and FGF7/THBS1, respectively (here, fibroblasts and CAFs were combined as overall CAFs since the former might transform into the latter in tumour conditions)." (PMID 38778448, 2024). "Similarly, engineering CAR T cells against MUC1, EpCAM, and EGFR could harness their roles in tumor progression and resistance to conventional therapies, offering a novel approach to overcome these challenges." (PMID 39335203, 2024). "Moreover, MUC1 can promote the phosphorylation of extracellular signal-regulated kinase 1/2 (ERK1/2) and AKT by binding to galectin-3 (GAL3), enhancing cancer cell adhesion to vascular endothelial cells and tumor invasiveness." (PMID 39491020, 2024). "In addition, we performed immunohistochemical staining of paired primary tumor and lung metastasis tissue sections from the same patient and found that PDL1 levels were higher in lung metastases than in primary tumors, and that MUC1 was positively correlated with PDL1 (r = 0.3919, P = 0.0219)." (PMID 36738352, 2023). "In particular, our in silico and in situ studies demonstrate that MUC1 (EMA) could be an attractive target in PSMA-negative tumors, since on the patient, metastasis, and individual tumor cell levels, we observed an inverse correlation between MUC1 and PSMA expression." (PMID 36821396, 2023). "In these studies, the intensity of MUC1 expression in the tumor was not taken into account." (PMID 36367122, 2023). "In contrast, the perihilar tumor exhibited positive for MUC1 and MUC5AC, but negative for MUC2." (PMID 37721561, 2023). "All in all, these results highlighted the relevance of the expression of chemokines such as CXCL13 and the lack of expression of the transmembrane oncoprotein MUC-1 as surrogate markers of the anti-tumor immune response mediated by activated lymphocytes in the TME." (PMID 36765559, 2023).